SNORA11E (small nucleolar RNA, H/ACA box 11E)
Gene: Small nucleolar RNA gene on chromosome X (52,063,347 to 52,063,474, reverse strand). Ensembl gene ENSG00000221705.
Gene Ontology:
Biological process: RNA processing
Cellular component: nucleolus
Homologues: Paralogues in human: SNORA11D (100% identical), SNORA11F (94% identical), SNORA11B (90% identical), SNORA11C (89% identical), SNORA11 (85% identical), SNORA11G (75% identical).